ENSG00000252852
Gene: Small nucleolar RNA gene on chromosome 8 (117,313,528 to 117,313,661, forward strand). Ensembl gene ENSG00000252852.
Homologues: Paralogues in human: SNORA31B (80% identical), SNORA31 (66% identical).